DPP4 (dipeptidyl peptidase 4)
Diseases named in the same sentence as DPP4 in open-access papers (continued):
Sharing a sentence is not in itself a finding about the gene and the disease.
asthma (39 papers, 2007 to 2026). "Another goal of this study was to examine the association between serum DPP4 levels and T2-high asthma, along with asthma features or conventional markers in the Chinese population." (PMID 38335422, 2024). "Interleukin 13 (IL-13) secreted by Th2 cells is associated with airway inflammation in asthma, and data based on transcriptome sequencing of asthmatic patients confirmed that a positive correlation exists between the DPP4 gene and IL-13 mRNA levels." (PMID 35967302, 2022). "Adult asthma-induced CD26/DPP4-deficient rats exhibited an attenuated inflammation combined with a reduced influx of regulatory T cells and a reduced upregulation of surfactant proteins." (PMID 34606000, 2021). "Kruschinski found that DPP4-dependent T cells were recruited to the lung in a rat asthma model, while in DPP4-deficient rats T cells obviously decreased." (PMID 34955820, 2021). "In an animal model of asthma using DPP4 (CD26)-deficient rats, it was reported that CD4-positive T-cell migration decreased even with IL-13 stimulation." (PMID 26975422, 2016). "In previous studies, it has often been pointed out that DPP4 is linked to airway inflammation in animal models of asthma." (PMID 26975422, 2016). "Another report demonstrated that the migration of CD4-positive T cells was decreased in a DPP4 (CD26)-deficient rat model of asthma." (PMID 26975422, 2016). "Such up-regulation in DPP activities by increasing expression of other functional homologous DPP has been previously reported in an experimental asthma DPP4-deficient rat model." (PMID 23517567, 2013). "In contrast to the beneficial effects of a genetically induced CD26/DPP4 deficiency in a rat model of experimental asthma, an aggravation of the inflammatory response was found under a continuous oral pharmacological inhibition of DPP4." (PMID 24303167, 2013). "Notably, DPP-4 inhibitors were associated with an increased risk of asthma, which warrants clinical caution." (PMID 41567683, 2025). "Additionally, we aimed to identify asthma characteristics and conventional markers associated with serumYKL-40 or serum DPP4 levels." (PMID 38335422, 2024). "Additionally, we sought to explore the associations of serum YKL-40 and DPP4 levels with asthma characteristics and conventional markers." (PMID 38335422, 2024). "Finally, 10 small-molecule drugs targeting high-risk asthma were screened using the cMAP database, and their correlation with DPP4 targets was significant." (PMID 35967302, 2022). "The level of DPP4 increases in airway epithelial cells of asthmatic patients, and its ability to promote airway smooth muscle cell proliferation in vitro implied that DPP4 is likely associated with airway remodeling in asthma." (PMID 35967302, 2022). "Furthermore, genetic deficiency of CD26/DPP4 exerts protective effects in experimental asthma." (PMID 24303167, 2013). "Both SGLT2 inhibitors and GLP-1 receptor agonists showed lower odds of asthma compared with DPP-4 inhibitors and placebo, while SGLT2 inhibitors also demonstrated lower odds of COPD, respiratory failure, and bronchitis versus placebo." (PMID 41567683, 2025). "This study aimed to assess the utility of serum YKL-40 and serum dipeptidyl peptidase IV (DPP4) as biomarkers for distinguishing between type 2 (T2)-high and T2-low asthma in the Chinese population." (PMID 38335422, 2024). "Logistic regression models were employed to further explore the relationship between the serum levels of YKL-40 and DPP4 with T2-high asthma." (PMID 38335422, 2024). "Assays on the anti-IL-13 antibody Tralokinumab reported a possible positive effect in a specific sub-group of patients with severe uncontrolled asthma and levels of serum dipeptidyl peptidase-4 (DPP-4) or periostin higher than the baseline median population." (PMID 36675006, 2023). "Serum DPP‐4 is generally similar in asthma patients compared to healthy controls (HCs), or lower in patients with more severe asthma." (PMID 37102668, 2023).
asthma (continued). "DPP4 also has an effect on different lung problems such asthma, chronic obstructive pulmonary disease, pulmonary fibrosis and middle east respiratory syndrome." (PMID 37624423, 2023). "On the basis of DEGs of high-risk patients, the cMAP database identified targets and drugs with potential therapeutic value for asthma, among which DPP4 demonstrated the highest enrichment score as a drug action target." (PMID 35967302, 2022). "Lastly, DPP-4 has been reported to possess a deleterious role and potential to be used as a biomarker in respiratory diseases, such as lung cancer, asthma, and chronic obstructive pulmonary disease (COPD)." (PMID 36551790, 2022). "A whole-transcriptome RNA sequencing study of nasal epithelial cells in children with asthma indicated that the DPP4 gene had a positive relationship with IL-13 mRNA level." (PMID 34955820, 2021). "DPP4 levels are elevated in airway epithelial cells in asthma patients, and DPP4 can stimulate the proliferation of lung fibroblasts and bronchial SMCs in vitro." (PMID 34955820, 2021). "Studies have mentioned the relationship between DPP-4 inhibitors and infection, asthma, and lung injury." (PMID 31013793, 2019). "In this study, ITLN-1 mRNA significantly correlated with FeNO and serum IgE, as well as iNOS, CCL26, periostin and DPP4 mRNA in SN-Asthma, as these genes are known to be induced in BECs stimulated with IL-13." (PMID 28775743, 2017). "The expression of DPP4 mRNA measured by qPCR in freshly isolated BECs obtained from asthma patients by bronchial brushing was significantly higher in snBA compared with stBA, in distal airway samples." (PMID 26975422, 2016). "We also investigated the expression of DPP4 in asthma patients and non-asthma patients who had undergone surgery for lung cancer." (PMID 26975422, 2016). "First, DPP4 expressions were enhanced in the BECs of asthma patients, especially in snBA, and also in BECs stimulated by IL-13." (PMID 26975422, 2016). "The distribution of DPP4 protein was determined by immunostaining of transbronchial lung biopsy specimens from asthma patients." (PMID 26975422, 2016). "To investigate the involvement of DPP4 in airway remodeling in asthma patients, we examined the proliferative effect of rhDPP4 on HFL-1 and BSMCs." (PMID 26975422, 2016). "Significant correlations were seen between DPP4 mRNA expression in the distal airways and eNO in asthma patients." (PMID 26975422, 2016). "The aim of this study was to investigate the expression of DPP4 in the asthmatic airway, and its role in the pathophysiology of asthma." (PMID 26975422, 2016). "In our study, a thorough investigation using microarray analysis, qPCR and ELISA was conducted and we found that DPP4 expression and production were induced in both BECs from asthma patients and in cultured BECs stimulated by IL-13." (PMID 26975422, 2016). "In contrast, DPP-4 inhibitors were associated with a significantly increased risk of asthma (OR 1.70, 95% CI 1.03–2.82; p = 0.039; I2 = 8.2%), without evidence of heterogeneity." (PMID 41567683, 2025). "For example, periostin and DPP-4 are being explored as potential predictors for IL-13-targeting biologics in asthma, while IL-33 and soluble IL-33R levels in sputum or serum may aid in selecting therapies that inhibit IL-33 signaling." (PMID 40004611, 2025). "In contrast, GLP-1 receptor agonists and DPP-4 inhibitors did not demonstrate a significant impact on asthma risk." (PMID 39768911, 2024). "Relationship between serum levels of YKL-40 and DPP4 with T2-high asthma in different models." (PMID 38335422, 2024). "The primary objective of this study was to investigate whether serum YKL-40 or serum DPP4 levels could effectively differentiate between T2-high and T2-low asthma among Chinese adults." (PMID 38335422, 2024). "Levels of soluble DPP4 protein and DPP4 activity were also higher in patients with obese asthma." (PMID 37287831, 2023).
asthma (continued). "Small molecules obtained from the cMAP database that may have therapeutic effects on asthma are mainly DPP4 inhibitors." (PMID 35967302, 2022). "Notably, the resulting DPP4 inhibitor sitagliptin predicted in this study can ameliorate airway inflammation in murine asthma models by downregulating inflammatory factors, such as IL-13." (PMID 35967302, 2022). "In addition, DPP4 mRNA was shown to be induced by IL-13, indicating the potential role of DPP4 in asthma." (PMID 34955820, 2021). "We speculate that when a pathogenic infection exists in the lungs of children, the downregulation of DPP4 will lead to an immune imbalance and inflammatory cascade reaction to affect the formation of lung substances, thus inducing asthma." (PMID 33194371, 2020). "Furthermore, IL-13-induced periostin and DPP4 can be measured in peripheral blood and are used as biomarkers to predict the efficacy of anti-IL-13 antibodies in human asthma patients." (PMID 28775743, 2017). "DPP4 is a one the gene that variable in untreated asthma and IL-13 stimulation." (PMID 26975422, 2016). "We demonstrated that DPP4 is expressed in BECs in human asthma and is induced by IL-13." (PMID 26975422, 2016). "Also, in vivo studies on the effect of DPP4 or DPP4 inhibitors using animal models of asthma will be needed." (PMID 26975422, 2016). "However, despite this compelling evidence for a role of CD26/DPP4 in asthma, so far the impact of pharmacological inhibition of DPP4 on allergic airway inflammation has not been studied." (PMID 24303167, 2013). "Hypothesizing that a CD26bright “late-memory” T-cell subpopulation plays an important role in the sensitization to an allergen, a systemic inhibition of CD26/DPP4 at the time point of sensitization should have implications for the course of asthma." (PMID 24303167, 2013). "In addition, our group has previously shown changes associated with asthma in the serum levels of many of the proteins detected in urine, i.e., IGFALS, FCN2, HSPG2, CD26/DPP4, and CD14, and suggested their use as potential phenotype/severity biomarkers of this disease." (PMID 39858454, 2025). "Hence, DPP4 was postulated as a potential biomarker for T2-high asthma." (PMID 38335422, 2024). "Soluble DPP4 may be a potential therapeutic target for obese asthma." (PMID 37287831, 2023). "Moreover, levels of DPP4 in the serum samples of asthma patients have been proposed as a type 2 inflammation marker and may predict the therapeutic efficacy of an IL-13 neutralizing antibody in a clinical trial." (PMID 37287831, 2023). "This indicates that DPP4 may participate in the occurrence of asthma by regulating T cells." (PMID 34955820, 2021). "In addition, studies have demonstrated that DPP4 on in vivo-derived EVs is enzymatically active, suggesting that airway DPP4+ EVs may participate in these mechanisms in asthma." (PMID 32560723, 2020). "Comparison of samples from asthma patients that were immunostained with control isotype IgG or with an anti-DPP4 antibody (representative snBA patient) indicated that the DPP4 protein was strongly expressed in BECs and in inflammatory cells such as eosinophils, macrophages and lymphocytes." (PMID 26975422, 2016). "Meanwhile, the T2-low asthma group showed median serum levels of YKL-40 and DPP4 at 30.9 ng/mL (Q1–Q3: 17.0–44.4) and 1105.5 ng/mL (931.4–1444.8), correspondingly." (PMID 38335422, 2024). "Within the T2-high asthma group, the median serum levels of YKL-40 and DPP4 were 38.8 ng/mL (Q1–Q3: 25.7–66.9) and 1076.4 ng/mL (Q1–Q3: 968.6–1227.0), respectively." (PMID 38335422, 2024). "Another DPP4 inhibitor, saxagliptin, was reported to alleviate airway inflammation in ovalbumin (OVA)-induced asthma in mice via the NF-κB and TLR4 pathways." (PMID 34955820, 2021). "Dipeptidyl peptidase-4 (DPP-4) is expressed in different lung cells, but its role in human asthma is uncertain." (PMID 34070316, 2021).
asthma (continued). "Prior to our research on DPP-4 inhibitors and allergic rhinitis (AR), we found a previous study talked about the effect of DPP-4 inhibitors on asthma control." (PMID 31013793, 2019). "In the SN-Asthma group, ITLN-1 mRNA correlated with FeNO, IgE, iNOS, CCL26, periostin and DPP4 mRNA, all Type-2 related parameters." (PMID 28775743, 2017). "However, the role of DPP4 in the pathogenesis of asthma is still unclear, and revealing this role could potentially lead to greater understanding of the pathophysiology and treatments of asthma." (PMID 26975422, 2016). "Therefore, CD26/DPP4 might represent a novel therapeutic target in asthma." (PMID 24303167, 2013). "Increased gene expression of DPP4, 8 and 9 and increased DPP enzymatic activity following asthma induction occurs in mice, suggesting that pan-DPP inhibition might be protective in asthma." (PMID 40293537, 2025). "Our analysis using logistic regression models on Chinese stable asthma patients revealed that neither serum YKL-40 nor serum DPP4 levels significantly distinguished between T2-high and T2-low asthma." (PMID 38335422, 2024). "DPP4 also affects other infectious respiratory diseases such as Middle East respiratory syndrome and non-infectious lung diseases such as pulmonary fibrosis, lung cancer, chronic obstructive pulmonary disease (COPD), and asthma." (PMID 34955820, 2021). "Another phase 2b study of tralokinumab showed a nonsignificant reduction of the asthma exacerbation rates, and somewhat encouraging results were observed in a subgroup of patients with higher baseline levels of dipeptidyl peptidase (DPP)-4 and periostin." (PMID 29155876, 2017). "As this inhibitor ile-thia is unspecific for DPP4 also affecting DPP4 homologues, we furthermore investigated the effects of ile-thia in a rat model of asthma using F344 rats genetically lacking DPP4 expression and DPP4 activity." (PMID 24303167, 2013). "However, in this study, we observed that serum DPP4 levels did not play a role in distinguishing between T2-high and T2-low asthma." (PMID 38335422, 2024). "However, neither serum YKL-40 nor serum DPP4 levels exhibited the capability to differentiate between T2-high and T2-low asthma." (PMID 38335422, 2024). "As a result of increased expression of DPP-4, which is induced by the type 2 cytokines interleukin (IL)-4 and IL-13, in diseases of asthma and type 2 inflammation, such as atopic dermatitis and chronic rhinitis, DPP-4i may help with the management of asthma." (PMID 37025413, 2023). "In the field of asthma research, one study revealed that DPP4 mRNA expression was induced by IL-13 stimulation of normal human BECs by microarray analysis but it did not examined DPP4 in detail." (PMID 26975422, 2016). "However, the localization of DPP4 in the airway in non-treated asthma patients and the direct effects of DPP4 on the pathophysiology of asthma are not fully understood." (PMID 26975422, 2016). "Moreover, it provided inaugural confirmation that neither serum YKL-40 nor serum DPP4 could effectively distinguish between T2-high and T2-low asthma in adult Chinese asthma patients." (PMID 38335422, 2024). "Nevertheless, existing literature has failed to establish a link between serum DPP4 and type 2 inflammatory biomarkers, including FeNO, blood and sputum eosinophils, and Immunoglobulin E. Until now, it was unclear if serum DPP4 can effectively distinguish asthma endotype." (PMID 38335422, 2024). "Until now, it has been hypothesized that CD26/DPP4 plays a crucial role in the onset and course of allergic inflammations, but to our knowledge no experimental studies trying to modulate asthma have been published." (PMID 24303167, 2013). "First, in our retrospective clinical cohort of obese asthma, eosinophil data in BAL fluid was not available, which prevented us from correlating palmitic acid and DPP4 levels with airway eosinophilic inflammation in human subjects." (PMID 37287831, 2023).
type 1 diabetes (39 papers, 2011 to 2026). "DPP-4 inhibitors appeared safe in patients with type 1 diabetes compared to placebo (risk ratio [RR] = 1.00; 95% CI: 0.77–1.31; p = 0.98)." (PMID 41026724, 2025). "Mechanistically, PRDX4 promoted the degradation of dipeptidyl peptidase-4, which is associated with DR in type 1 diabetics, thereby alleviating HG-stimulated Müller cell abnormalities." (PMID 39706273, 2024). "Elevated DPP4 activity has been detected in diabetic individuals, and its circulating levels have been linked to DR in type 1 diabetes." (PMID 39706273, 2024). "Additional large-scale, long-term studies are needed to better define the impact of DPP-4 inhibitors on HbA1c and β-cell function in patients with type 1 diabetes." (PMID 41026724, 2025). "In conclusion, DPP-4 inhibitors appear to be safe as adjunctive therapy to insulin in patients with type 1 diabetes." (PMID 41026724, 2025). "This meta-analysis evaluated the impact of adding DPP-4 inhibitors to insulin therapy, focusing on glycemic control as assessed by HbA1c, insulin requirements, and the implications for patients with type 1 diabetes." (PMID 41026724, 2025). "Patients with type 1 diabetes have elevated serum DPP4 activity and reduced DPP4 expression in the lymphocyte membrane." (PMID 38127960, 2024). "Numerous clinical studies have shown the beneficial therapeutic effects of DPP-4 inhibitors in type 1 diabetes, where they decreased prandial insulin dose and total daily dose (TDD) of insulin, inhibited glucagon secretion and reduced blood glucose levels." (PMID 39271520, 2024). "Several previous studies showed that patients within type 1 diabetes had decreased DPP-4 expression of lymphocyte membrane but increased serum DPP-4 activity." (PMID 37350750, 2023). "For instance metalloproteinase-9 (MMP9) is augmented in the sera of systemic lupus erythematosus patients and dipeptidyl peptidase-4/CD26 (DPP4/CD26) in sera of type 1 diabetes, rheumatoid arthritis, systemic lupus erythematosus and inflammatory bowel disease." (PMID 34220840, 2021). "Previously, a study showed that plasma DPP4 levels and DPP4 mRNA expression in tissues increased progressively during the development of streptozotocin-induced type 1 diabetes." (PMID 34043673, 2021). "Using the same STZ-induced CD-1 murine model of type 1 diabetes, the author and colleagues subsequently identified a new profibrotic molecular mechanism comprising an interaction between DPP-4 and integrin β1 in endothelial cells." (PMID 29491123, 2018). "This study aimed to investigate the potential of an oral formulation (QV formulation) containing Quercetin and a Dipeptidyl Peptidase-4 Inhibitor (DPP-4 inhibitor), Vildagliptin, in improving metabolic homeostasis in type 1 diabetes model." (PMID 30333575, 2018). "Therefore, the aim of this meta-analysis it to systematically summarize the evidence on adding DPP-4 inhibitors to insulin therapy in patients with type 1 diabetes." (PMID 41026724, 2025). "Thus, an updated systematic review and meta-analysis on DPP-4 inhibitors usage as an adjunct therapy on type 1 diabetes is necessary." (PMID 41026724, 2025). "Another study indicated that a combination of Vitamin D and dipeptidyl peptidase-4 (DPP-4) inhibitors preserved β-cell function and prolonged disease remission phases in type 1 diabetes, demonstrating synergistic anti-inflammatory and immune-regulatory effects." (PMID 39857603, 2024). "DPP-4 is a multifunctional serine protease that regulates immune cell-mediated β cell destruction and immune cell function, thereby prolonging the progression of type I diabetes mellitus." (PMID 38379936, 2024). "For the promising effect on β cell protection, DPP4-Is have been studied in humans for the treatment of Type 1 diabetes (T1DM) and LADA and data showed better glycemic control in patients treated with DPP4-Is in addition to a traditional insulin regimen in comparison to insulin alone." (PMID 36140405, 2022).